NLRP3 (NLR family pyrin domain containing 3)
Diseases named in the same sentence as NLRP3 in open-access papers (continued):
Sharing a sentence is not in itself a finding about the gene and the disease.
Sepsis (continued). "In the context of sepsis, NLRP3 functions by recruiting and activating caspase-1, leading to release of IL-1β and IL-18, initiating a cascade of inflammatory reactions that ultimately leads to substantial inflammation-induced damage and multi-organ failure." (PMID 39364223, 2024). "Upregulated YTHDF1 causes NLRP3 translation, and YTHDF1 deficiency promotes survival of sepsis mice." (PMID 38874470, 2024). "Studies have found that NLRP3/caspase‐1/GSDMD‐mediated pyroptosis plays an important role in the occurrence and development of sepsis, and inhibiting NLRP3 inflammasome‐mediated pyroptosis can reduce acute lung injury in sepsis." (PMID 39484787, 2024). "NLRP3-mediated macrophage pyroptosis plays a pivotal role in sepsis-induced ALI by exacerbating inflammation and organ damage." (PMID 39300342, 2024). "Pyroptosis, a proinflammatory cell death caused by caspase-1 during infection, is increasingly seen as a key mechanism of sepsis, mediated by NLRP3 inflammasome activation." (PMID 38705396, 2024). "Here, we identified the deubiquitinase YOD1, which played a vital role in regulating coagulation in a NLRP3 inflammasome-dependent manner in sepsis induced by methicillin-resistant Staphylococcus aureus (MRSA)." (PMID 38789414, 2024). "In PBMCs from patients with sepsis, the mRNA levels of miR-21 and NLRP3 were significantly increased, and the mRNA level of A20 was decreased." (PMID 38169584, 2024). "Maintaining the stability of the ER seems crucial in preventing excessive activation of the NLRP3 inflammasome, decreasing caspase-1-mediated pyroptosis, and enhancing sepsis results." (PMID 38434710, 2024). "In another report, the mechanism of FXR negatively regulating the NLRP3 inflammasome was through FXR interacting with NLRP3, as well as caspase 1 in protein levels during sepsis associated with cholestasis." (PMID 38172440, 2024). "In a patient study, serum-derived EVs and macrophages from sepsis patients have elevated levels of HMGB1, which activates the NLRP3 inflammasome and causes liver damage." (PMID 39770410, 2024). "Inhibiting pyroptosis by inhibiting NLRP3 and caspase-1 expression has shown protective effects on cognitive impairment following sepsis in newborn rats." (PMID 38665289, 2024). "Despite this known function, the specific mechanism of WNK1 in NLRP3-mediated macrophage pyroptosis and its role in sepsis-induced lung injury remains unelucidated." (PMID 39300342, 2024). "We verified that HSPA8 inhibited sepsis-induced lung injury by promoting NLRP3 ubiquitination by constructing pcDNA3.1-HSPA8 and adeno-associated virus AAV9-HSPA8." (PMID 38698431, 2024). "Successful prevention or treatment of sepsis, peritonitis, and type II diabetes in mice was demonstrated by knocking out the NLRP3 gene and suppressing the activation of the NLRP3 inflammasome." (PMID 38169577, 2024). "The results demonstrated that PBMCs from the sepsis group had significantly higher relative protein levels of NLRP3, caspase-1, cleaved GSDMD, and IL-1β than those from the control groups." (PMID 38169584, 2024). "Inhibits sepsis mediated by NLRP3-Caspase-1-GSDMD and has neuroprotective properties in various neurological disorders such as HD, AD, epilepsy, cognitive disorders, anxiety disorders, and depression." (PMID 38370420, 2024). "During infection and sepsis, the NLRP3-inflammasome initiates pro-caspase-1 activation via auto-proteolysis." (PMID 38410714, 2024). "AMs and the NLRP3 play key roles in determining the immune landscape following sepsis, with implications for lung injury." (PMID 39405117, 2024). "In this study, we show that SKP2, as an E3 ubiquitin ligase, its suppression attenuate NLRP3 protein ubiquitination and subsequently promote NLRP3 inflammasome activation in sepsis." (PMID 38698431, 2024). "By reducing the expression of the PERK/ATF4/CHOP signaling pathway, the NLRP3 inflammasome’s hyperactivation and caspase-1-dependent pyroptosis are inhibited, which improving sepsis outcomes." (PMID 38434710, 2024).
Sepsis (continued). "As major DAMPs, extracellular histones significantly contributed to NLRP3 inflammasome activation and subsequent pyroptosis during sepsis and acute lung injury." (PMID 39206200, 2024). "Interfering with the C5a and NLRP3 inflammasome complex can mitigate histone appearance in polymicrobial sepsis models." (PMID 39201339, 2024). "The results showed that NLRP3−/− mice with burn sepsis had 30% increased survival and bacterial clearance at the injury site compared with WT mice with burn sepsis." (PMID 38957662, 2024). "Our previous study demonstrated that sepsis-triggered canonical NLRP3 inflammasome activation cleaved GSDMD in the hippocampus, inducing neuronal pyroptosis and neuroinflammation, causing hippocampus-dependent memory impairments." (PMID 38627764, 2024). "Our previous studies have shown that MS can suppress the NLRP3 signaling pathway to alleviate sepsis-induced intestinal injury." (PMID 37898993, 2024). "As sepsis progresses, the levels of NLRP3 and IL‐18 also increase, further aggravating renal tubular damage and leading to progressive decline in renal function." (PMID 39692606, 2024). "Our data confirmed that ERS was overactivated during sepsis, which facilitated ERS-associated NLRP3 activation." (PMID 38816685, 2024). "This suggests that the regulation of NLRP3 ubiquitination by SKP2 is involved in the process of lung injury in sepsis." (PMID 38698431, 2024). "Targeting the CaMKII/NLRP3 axis has been proven to mitigate sepsis-induced cardiac injury by reducing pyroptosis." (PMID 39290498, 2024). "Targeted inhibition of the NLRP3 inflammasome heralds a new therapeutic intervention to improve burn sepsis and its poor prognosis." (PMID 38957662, 2024). "Pharmacological inhibition of NLRP3 not only reduces the expression of IL-1β, but also alleviates cognition impairment after sepsis." (PMID 38665289, 2024). "Studies have also suggested that the administration of inhibitors of NLRP3/caspase-1 pathway-mediated pyroptosis (e.g., MC950, melatonin) is protective against sepsis-associated encephalopathy, spinal cord injury, and motor neuron damage in rats." (PMID 38256033, 2024). "Sepsis often induces severe oxidative stress, and the accompanying accumulation of ROS is a crucial factor in the increase in NLRP3 expression and activation." (PMID 39224841, 2024). "Irisin treatment suppressed inflammation, apoptosis, and pyroptosis by blocking the Toll-like receptor 4 (TLR4) and NLRP3 inflammasome signaling in vivo and in vitro and attenuated myocardial dysfunction in sepsis." (PMID 38540711, 2024). "Our investigations into the DKO mice have revealed a substantial modulation of the NLRP3/Ym1 pathway during sepsis." (PMID 39405117, 2024). "Liu et al60 reports that buformin, a hypoglycemic agent, suppresses NLRP3‐mediated pyroptosis via enhancing autophagy in sepsis‐induced ALI." (PMID 38758159, 2024). "The major finding in the present study was that ACSS2 was found to act as a critical regulator of activation of the NLRP3 inflammasome and pyroptosis in RTECs in vitro and in vivo LPS-induced sepsis models of AKI." (PMID 38515158, 2024). "ADAR1 attenuated sepsis-induced lung injury and hindered the activation of pyroptosis in pulmonary macrophages in sepsis through the miR-21/A20/NLRP3 axis." (PMID 38169584, 2024). "Baseline serum NLRP3 levels had significant predictive value for 28-day mortality in sepsis patients complicated with ARDS." (PMID 37649483, 2023). "In particular, NLRP3 serves as a downstream effector for NR1H3‐initiated myocardial benefits during sepsis." (PMID 37206244, 2023). "In a mouse model of sepsis, NLRP3 knockout reduced caspase-1 and IL-1b/IL-18 levels in the kidney and attenuated kidney injury." (PMID 36674930, 2023). "The ROS-dependent NLRP3 inflammasome activation was also observed in LPS-induced cardiomyocyte injury and sepsis‐induced brain injury." (PMID 37596540, 2023).
Sepsis (continued). "NLRP3, the platform of proinflammatory cytokine maturation and secretion, plays a critical role in sepsis." (PMID 37206244, 2023). "Another study reported that S100A12 promoted inflammation in sepsis-induced acute respiratory distress syndrome by activating the NLRP3 inflammasome signaling pathway." (PMID 37671148, 2023). "Future studies were necessary for the determination of the clinical utility of serum NLRP3 in the diagnosis of sepsis patients with ARDS." (PMID 37649483, 2023). "Reduced IL‐1β serum levels in septic Nlrp3 KO mice are accompanied by reduced cardiac and cardiomyocyte atrophy, improved cardiac diastolic and systolic function, and increased sepsis survival compared with septic WT mice." (PMID 37904696, 2023). "Circulating histones, as DAMPs in sepsis, have been reported to induce pyroptosis through the NLRP3 inflammasome in human umbilical vein endothelial cells, which further results in the expression of endothelial adhesion molecules and an inflammatory response." (PMID 36756123, 2023). "Sepsis up-regulates both NLRP3 and IL-1β expression in whole muscle, ultimately leading to elevated concentrations of circulating IL-1β." (PMID 37447158, 2023). "Our works showed that HSF1 plays an important role in sepsis-induced brain injury by regulating NLRP3." (PMID 36741074, 2023). "Activation of the TGF-β/NLRP3/caspase-1 signaling pathway stimulates pyroptosis, which ultimately exacerbates sepsis-induced acute kidney injury." (PMID 38102696, 2023). "The NLRP3 inflammasome, the most widely researched inflammasome in the kidney, is crucial in the pathogenesis of sepsis and acute kidney injury." (PMID 37759588, 2023). "In a mouse model of LPS-induced sepsis, mice fed a ketone monoester had reduced markers of NLRP3 activation and markers of hepatic inflammation, including Il-1β and Tnfα." (PMID 37113697, 2023). "Recently, an increasing number of studies have found that E3 ligases are involved in the pathogenesis of sepsis by regulating the activation of the NLRP3 inflammasome through catalyzing ubiquitination of NLRP3 or other components of the inflammasome." (PMID 37465127, 2023). "Activation of the inflammatory NLRP3 inflammasome is an important mechanism by which macrophages combat invading pathogens in the early stages of sepsis." (PMID 36798132, 2023). "Previous studies have found that NLRP3 inflammasome participates in the pathogenesis of sepsis-induced kidney failure and sepsis-induced liver injury." (PMID 37649483, 2023). "Based on the previous description, LPs-induced Huh7 and HepG2 cells were used to establish cell models of septic liver injury to analyze the role of TXNIP-stabilizing USPs in the progression of sepsis-induced liver injury and in the NLRP3 inflammatory pathway." (PMID 37534934, 2023). "During gram‐negative bacteria infection, caspase‐11 activated by cytosolic LPS cleaves GSDMD, and the released N‐GSDMD mediates both pyroptosis and NLRP3 inflammasome activation, which promotes sepsis." (PMID 37090118, 2023). "A recent study revealed that sepsis-derived S100A8/A9 induces GSDMD-dependent platelet pyroptosis in severe sepsis by upregulating the TLR4/NLRP3 signaling pathway, which leads to the release of oxidized mtDNA and promotes NETs formation." (PMID 37275856, 2023). "We used this strategy to identify a naturally sourced small molecule, DP, which inhibits NLRP3 inflammasome activation via CMPK2 and, thus, is a potential treatment for inflammasome‐associated diseases such as sepsis." (PMID 37859535, 2023). "The study of ROS‐mediated activation and regulation mechanism of NLRP3 inflammasome in sepsis will provide theoretical guidance as well as new therapeutic targets for the treatment of sepsis‐induced cardiac dysfunction." (PMID 37904696, 2023).
Sepsis (continued). "We have reported that inhibition of SphK1 improved the survival and lung vascular leakage in mice with cecal ligation and puncture (CLP)-induced sepsis by impeding NLRP3 inflammasome activation and subsequent IL-1β release from macrophages." (PMID 36798132, 2023). "Recent evidence has demonstrated estrogen limits sepsis‐induced liver injury by blocking ROS‐regulated NLRP3 activation." (PMID 36705411, 2023). "It is very important to find a possible molecular pathway for alleviating pyroptosis through NLRP3 in brain tissue and nerve cell lines, which can shed light on the mechanism to protect brain tissue in sepsis." (PMID 36741074, 2023). "In a study on sepsis mice with a cognitive impairment model, the importance of the NLRP3-IL-1β pathway in the transition from acute peripheral inflammation to chronic central neuritis was reported." (PMID 37009097, 2023). "ATP is a common NLRP3 stimulus that was released in large quantities during sepsis, contributing to systemic inflammation and secondary organ damage." (PMID 36798132, 2023). "This mechanistic finding was validated in mouse models of sepsis and periodontitis, which were NLRP3 inflammasome activation dependent." (PMID 37051938, 2023). "Previous studies have shown that inhibition of NLRP3 inflammasome activation results in protective effects against sepsis." (PMID 36756123, 2023). "Studies on sepsis have shown that TNF-α upregulates the expression of NLRP3 through the NF-κB signaling pathway, induces polarization of macrophages to M1 macrophages and causes pyroptosis of lung macrophages, leading to histological lesions." (PMID 37686375, 2023). "Overall, the experimental results clarify that DP has tremendous development value for novel therapies targeting NLRP3‐driven diseases such as sepsis." (PMID 37859535, 2023). "Recently, soluble forms of P2X7R and NLRP3 (sP2X7R and sNLRP3) were shown to be elevated in inflammation and sepsis, and tentatively added to the panoply of inflammatory mediators." (PMID 37215142, 2023). "To further validate the anti‐inflammatory effect and mechanism of the nano‐windmill in vivo, we established a sepsis model that is NLRP3 inflammasome dependent." (PMID 37051938, 2023). "Mangiferin, a flavonoid widely distributed in several herbs, inhibited NLRP3/caspase-1/-11-mediated GSDMD activation in sepsis." (PMID 38022612, 2023). "In summary, studies have shown that NLRP3 activation plays a critical role in the pathogenesis of sepsis-induced ARDS." (PMID 37649483, 2023). "Blockage of NLRP3, using a selective inhibitor, led to decreased platelet activation and offered protection from organ dysfunction in rats with sepsis." (PMID 37081895, 2023). "Juan José Martínez-García found that hypoxia-inducible factor (HIF)-1 α is activated, possibly through the influence of its P2X7 receptor on HIF-1 α, and that inhibition of NLRP3 leads to mitochondrial damage in the monocytes of patients with sepsis." (PMID 36937929, 2023). "Our findings provide promising insights into the potential utility of serum NLRP3 in the diagnosis and prognosis of sepsis complicated with ARDS." (PMID 37649483, 2023). "Next, they used LPS-induced sepsis and alum-induced peritonitis models with these mice, adding evidence for reduced NLRP3-dependent inflammatory responses in vivo." (PMID 38022631, 2023). "Downregulated NLRP3 can suppress pyroptosis and protect the endothelium from early sepsis, and the inhibition of the NLRP3 inflammasome can prevent sepsis." (PMID 36741074, 2023). "The NLRP3 inflammasome, a complex responsible for IL-1β and IL-18 release and a crucial mediator of pyroptosis, became activated in platelets in a sepsis rat model and correlated with lung and renal injury." (PMID 37081895, 2023). "Blocking the activation of NLRP3 inflammasome and inhibiting the signaling pathway of NLRP3 can alleviate sepsis-induced lung injury." (PMID 38035100, 2023).
Sepsis (continued). "In support of this clinical observation, the SARS-2-N protein aggravates lung injury and accelerates cell death in sepsis and acute lung inflammation mouse models by facilitating NLRP3 inflammasome assembly and promoting IL-1β production." (PMID 36936774, 2023). "Conversely, mitophagy-promoting miR-138–5p promoter demethylation subsequently inhibits NLRP3 inflammasome, AMs pyroptosis, and sepsis-induced ALI or ARDS in a CLP mouse model." (PMID 38027963, 2023). "NLRP3 inflammasome, promoter, circular RNA, myocardial injury, sepsis, and ROS represent the frontiers of cardiomyocyte apoptosis research and are in their outbreak period." (PMID 38013295, 2023). "This suggests that in the case of our Gram-negative, bacterial induced sepsis patients, there is an activation of the NLRP3 inflammasome pathway involved in the increased expression of S100A12 in the pathogenesis of sepsis-induced ARDS." (PMID 36979757, 2023). "YTH N6-Methyladenosine RNA Binding Protein 1 (YTHDF1), m6A reader protein, induced NLRP3 ubiquitination and inhibited caspase-1-dependent pyroptosis to alleviate sepsis." (PMID 38022612, 2023). "The N protein of SARS-CoV-2 directly binds to NLRP3 and triggers the formation of the NLRP3 inflammasome, thereby inducing excessive inflammatory response, acute lung injury, and accelerated sepsis-induced death." (PMID 37515138, 2023). "In this research, we try to explore the relationship between HSF1 and NLRP3 in a sepsis model and try to reveal the mechanism of HSF1 inhibiting the process of brain injury." (PMID 36741074, 2023). "We previously showed that IL‐1β serum levels and muscular Il6 expression were reduced in septic Nlrp3 KO mice, and that these mice are protected from muscle atrophy in sepsis." (PMID 37209006, 2023). "Of note, pyroptosis, a sort of programmed cell death driven by NLRP3 inflammasome activation, is a major contributor to sepsis." (PMID 36923408, 2023). "A large number of studies have shown that abnormal activation of NLRP3 inflammasome plays an important role in the pathogenesis and progression of sepsis." (PMID 37359543, 2023). "Inhibition of the NLRP3 inflammasome during sepsis can improve survival and bacterial clearance, and alleviate acute lung injury." (PMID 37600769, 2023). "NLR family pyrin domain-containing 3 (NLRP3) increased in the procession of sepsis and functioned as the key regulator of pyroptosis." (PMID 36741074, 2023). "Plantainoside D (PD), an effective component of Plantago asiatica L., significantly improved sepsis induced ALI by regulation of Sirt3/NLRP3 pathway." (PMID 37494665, 2023). "Increasing evidence have indicated that NLRP3 inflammasome and pyroptosis in macrophages are essential for the occurrence and development of sepsis." (PMID 36923408, 2023). "The NLRP3 inflammasome increased in the procession of sepsis and functioned as the key regulator of pyroptosis." (PMID 36741074, 2023). "The NLRP3 inflammasome modulates responses to sepsis by activation when cells are primed with cytokines or LPS and then stimulated with ATP, reactive oxygen species (ROS), mitochondrial dysfunction, or K+ efflux." (PMID 37600769, 2023). "We found that during sepsis, the elevated miR-15b-5p levels were related to vascular endothelial cell damage, robust inflammation, activation of the NLRP3 pathway, increased PCSK9 levels, and downregulation of SIRT4." (PMID 37587410, 2023). "Previous studies also confirmed that regulation of NLRP3 inflammasome activation can affect the occurrence and development of sepsis." (PMID 37465127, 2023). "NLRP3 inflammasomes trigger inflammation and promote immune cell apoptosis, thus contributing to the worsening of sepsis progression." (PMID 38129384, 2023). "Abnormal activation of NLRP3 inflammasomes has been widely considered as ideal drug targets for sepsis because of their important roles in the pathogenesis and progression of sepsis." (PMID 37359543, 2023).